SARS2 (seryl-tRNA synthetase 2, mitochondrial)
Description:
Catalyzes the attachment of serine to tRNA(Ser). Is also probably able to aminoacylate tRNA(Sec) with serine, to form the misacylated tRNA L-seryl-tRNA(Sec), which will be further converted into selenocysteinyl-tRNA(Sec).
Synonyms: SerRS; SARSM; FLJ20450; mtSerRS; SerRSmt; SARS; SERS; SYS
Tractability: Small molecule: a structure with a bound ligand is known. PROTAC: ubiquitination databases record sites on it; its protein half-life has been measured.
Gene: Protein-coding gene on chromosome 19 (38,915,266 to 38,930,768, reverse strand). Ensembl gene ENSG00000104835.
Subcellular location: Mitochondrion matrix
Subcellular location (Human Protein Atlas): Mitochondria; Nucleoplasm; Vesicles
Pathways (Reactome):
Metabolism of proteins: Mitochondrial tRNA aminoacylation
Gene Ontology:
Molecular function: protein binding; RNA binding; ATP binding; serine-tRNA ligase activity; tRNA binding; aminoacyl-tRNA ligase activity; nucleotide binding
Biological process: mitochondrial seryl-tRNA aminoacylation; seryl-tRNA aminoacylation; tRNA aminoacylation for protein translation
Cellular component: mitochondrion; mitochondrial matrix
Genetic constraint (gnomAD): Loss-of-function variants: 55 observed, 67.52 expected, observed/expected ratio (o/e) 0.81, 90% interval 0.65 to 1.02. The upper end of that interval is the gene's LOEUF score, 1.02, which puts it in group 4 of 6, group 1 being the genes least tolerant of losing a copy. Missense variants: 673 observed, 704.49 expected, observed/expected ratio (o/e) 0.96, 90% interval 0.9 to 1.02. Synonymous variants: 306 observed, 276.52 expected, observed/expected ratio (o/e) 1.11, 90% interval 1.01 to 1.22.
Gene-disease validity (ClinGen):
ClinGen rates the evidence that SARS2 causes each of these diseases.
mitochondrial disease (autosomal recessive): Moderate.
Homologues: Orthologues: chimpanzee SARS2 (99% identical), macaque SARS2 (95% identical), dog SARS2 (87% identical), rat Sars2 (86% identical), mouse Sars2 (86% identical), guinea pig SARS2 (86% identical), pig SARS2 (86% identical), rabbit SARS2 (83% identical), tropical clawed frog sars2 (58% identical), zebrafish sars2 (56% identical), Caenorhabditis elegans sars-2 (32% identical), Drosophila melanogaster SerRS-m (31% identical). Paralogues in human: SARS1 (22% identical).
Diseases named in the same sentence as SARS2 in open-access papers:
SARS2 is named in the same sentence as 36 diseases in open-access papers, as found by Europe PMC text mining. Sharing a sentence is not in itself a finding about the gene and the disease. The quoted sentences say what the papers report.
COVID-19 (15 papers, 2020 to 2024). A disease caused by infection with severe acute respiratory syndrome coronavirus 2. "COVID-19 reinfection has been clinically observed and we suspect it is associated with varying SARS2 variants." (PMID 33777970, 2021). "In this regard, we hypothesize that COVID-19 reinfection could potentially be linked to SARS2 FLC structural variations since SARS2 FLC affects viral pathogenesis, tropism, and transmissibility." (PMID 33777970, 2021). "It is known that severity of COVID-19 is tied to both elevated plasma IgA and IgG titers to SARS2 spike and receptor-binding domain (RBD) during acute infection." (PMID 36321826, 2022). "Coronavirus disease 2019 (COVID-19) pandemic has been attributed to SARS-CoV-2 (SARS2) and, consequently, SARS2 has evolved into multiple SARS2 variants driving subsequent waves of infections." (PMID 34745235, 2021). "Wild type mice (BALB/c, C57BL/6), immunodeficient mice (SCID), chimeric mouse expressing human angiotensin-converting enzyme 2 (hACE2), and the RNA-dependent RNA polymerase (SARS1/SARS2-RdRp) were evaluated as models of COVID-19." (PMID 33023604, 2020). "Last, our findings focused on primary infection with ancestral SARS2 and may not be reflective of all individuals with acute COVID-19, including primary infection by SARS2 variants or SARS2 breakthrough infections." (PMID 39704169, 2024). "Among the diagnosed cases of COVID-19 by RT-PCR, the median (IQR) of Ct value of SARS2 N gene was 18.5 (16.1-32.3) in TB patients (n=104), compared to 18.8 (15.1-30.0) in non-TB infected COVID-19 patients (n=57)." (PMID 39606691, 2023). "When evaluating their ability to detect antibodies in patients confirmed with COVID-19, Dx-SARS2-noRBD reacted with all patient samples without overlapping with the non-COVID-19 samples." (PMID 34579223, 2021). "Thus, early SARS2-specific CD4+ and CD8+ T cell responses were specifically associated with reduced upper airway SARS2 viral loads in unvaccinated, nonhospitalized cases of acute COVID-19." (PMID 39704169, 2024). "While T cell kinetics and phenotypes in response to SARS2 infection and COVID-19 vaccination may not be identical and are shaped by exposure history, the cumulative data now indicate that SARS2-specific T cells play a protective role in both primary SARS2 infection and breakthrough infections." (PMID 39704169, 2024).
HUPRA syndrome (7 papers, 2011 to 2024). "Mutations in the SARS2 gene, which encodes the mitochondrial seryl-tRNA synthetase, is believed to lead to the rare mitochondrial disease, HUPRA syndrome." (PMID 39711778, 2024). "We also noticed that SARS2 gene splicing defect caused progressive spastic paresis instead of HUPRA syndrome." (PMID 36698945, 2022). "Seryl-tRNA synthetase 2 (SARS2) gene variants are believed to cause HUPRA syndrome, and these variants result in the loss of function of seryl-tRNA synthetase." (PMID 36698945, 2022). "We then performed literature review to summarize SARS2 variants and clinical manifestations of HUPRA syndrome." (PMID 36698945, 2022). "The c.1205G > A (p.Arg402His) variant has been reported in previous case reports, and it was the most common SARS2 variant in HUPRA syndrome." (PMID 36698945, 2022). "Research has shown that HUPRA syndrome is caused by mutations in the seryl-tRNA synthetase 2 (SARS2) gene, which encodes seryl-tRNA synthetase (SerRS)." (PMID 36698945, 2022). "HUPRA syndrome is an ultrarare mitochondrial disease, SARS2 gene mutations are believed to cause HUPRA syndrome." (PMID 36698945, 2022). "The description of HUPRA syndrome and it genetic origin due to a mutation in SARS2 gene prompted us to sequence this gene in the patients II-1 and II-2." (PMID 24034276, 2013). "The genetic basis of HUPRA syndrome in Palestinian patients was a homozygous mutation (c.1169A > G p.D390G) in the SARS2 gene (RefSeq NG_031865.1), which encodes mitochondrial seryl‒tRNA synthetase." (PMID 24034276, 2013). "We confirmed that HUPRA syndrome was due to bi-allelic mutations in the SARS2 gene." (PMID 39664918, 2024). "Hyperuricemia, pulmonary hypertension, renal failure in infancy, and alkalosis (HUPRA syndrome) is a rare autosomal recessive mitochondrial disease with a prevalence of <1:1 000 000, due to variations in the seryl-tRNA synthetase (SARS2) gene encoding SARS on chromosome 19 (19q13.2)." (PMID 38264205, 2023). "For example, if a patient with SARS2 variants primarily sees a neurologist, HUPRA syndrome may be missed if the phenotype is subtle." (PMID 36553587, 2022). "To date, eight HUPRA syndrome patients and five kinds of variants of SARS2 have been reported." (PMID 36698945, 2022). "However, SARS2 gene splicing defect causes progressive spastic paresis instead of HUPRA syndrome., but we found that all variants causing HUPRA syndrome were single amino acid substitution." (PMID 36698945, 2022). "Interestingly, HUPRA syndrome is exclusively associated with SARS2, providing another example of unique mt-ARS phenotype." (PMID 36553587, 2022). "Several data support that p.R402H mutation in SARS2 is a new cause of HUPRA syndrome." (PMID 24034276, 2013). "The principal affected tissue in HUPRA syndrome by SARS2 mutations is the kidney." (PMID 24034276, 2013). "HUPRA syndrome is a mitochondrial disease that presents as pulmonary hypertension, which indicates a connection between SARS2 and pulmonary vascular remodeling." (PMID 36698945, 2022). "Missense mutations in the mitochondrial Seryl-tRNA Synthetase gene (SARS2) give rise to a multi-organ disease with Hyperuricemia, Pulmonary Hypertension, Renal Failure and Alkalosis (HUPRA-syndrome)." (PMID 21749694, 2011). "Thus, we believe that a single heterozygous mutation of SARS2 is not sufficient to cause HUPRA syndrome." (PMID 36698945, 2022).
viral infection (7 papers, 2020 to 2024). "To conclude, we demonstrate that mechanical force counter-intuitively impedes SARS2-S/ACE2 dissociation and induces subsequent S1/S2 rapid detachment for effective viral infection, and that D614G variation further enhances this mechano-regulation to increase SARS2 infectivity." (PMID 34465913, 2021). "Together, these results suggest that the force-dependent dissociation rate of RBD/ACE2 binding is a key factor for regulating both SARS2 and SARS viral infection." (PMID 34465913, 2021). "Collectively, these results indicate that SARS2/SNFPP+CMP+TEV-H8STREPH6 protein is an antigen that can strongly induce neutralizing antibodies and may provide sufficient protection from viral infection, especially in combination with Alum adjuvant." (PMID 35095889, 2021). "Consistent with this common role across distinct viral infections, we observed robust intersection between the CDK family HCTs (q-values: SARS1, 8e-23; SARS2, 2e-31; MERS, 1e-30) and the CDK6 HCTs (q-values: SARS1, 1e-7; SARS2, 8e-8; MERS, 3e-4) and those of all viral HCTs." (PMID 32511379, 2020).
pulmonary hypertension (3 papers, 2011 to 2022). Increased pressure within the pulmonary circulation due to lung or heart disorder. "Due to lack of research, whether mutations of SARS2 result in pulmonary hypertension via VEGFA pathways remains unknown and deserves further research." (PMID 36698945, 2022).
co-infection (2 papers, 2022 to 2025). "Investigating the interplay between FLUAV pre-exposure and SARS2 in the elderly population is imperative as FLUAV H1N1 was the most common detected co-infecting virus with SARS2, and patients with viral co-infection had more severe symptoms and required ICU admission in a recent study." (PMID 36279276, 2022).
hepatoma (2 papers, 2021 to 2024). "However, the spike 68–76 deletion within the NTD was identified in a human hepatoma cell clone termed Huh7.5-adapted-SARS2, indicating genetic adaptations." (PMID 39228849, 2024).
asthma (1 paper, 2020). "We also experimented with incorporating the directionality of the gene expression using the 2 asthma expression datasets and SARS2-DEG, since the direction of the DEGs are available in those 2 datasets." (PMID 33156843, 2020).
diabetes (1 paper, 2025). "Further studies will be needed to understand how disruption of mitochondrial protein translation by the m.3243A>G variant and variants in NARS2, SARS2, and TARS2 affects the β‐cell, leading to monogenic diabetes." (PMID 40887432, 2025).
measles (1 paper, 2024). A highly contagious viral infection caused by the measles virus. "Hence, the bona fide LLPC which may be a subset of the CD19neg BM ASC population likely harbors Flu- and Tet-specificities as well as measles- and mumps-specificities but appears to exclude SARS2-specific responses." (PMID 38559048, 2024).
metabolic acidosis (1 paper, 2016). "In addition, metabolic acidosis was prevalent among those with renal disease and transient alkalosis was only identified in a patient (P1) who was negative for SARS2 mutations." (PMID 27412952, 2016).
Varicose veins (1 paper, 2023). Enlarged and tortuous veins. "The colocalization analysis indicated that COLEC11, IRF3, LUM, POSTN, RSPO3, and SARS2 shared the same causal variant with varicose veins." (PMID 37404740, 2023). "The COLEC11, IRF3, LUM, POSTN, RSPO3, and SARS2 were considered to share the same variant of varicose veins." (PMID 37404740, 2023). "As a result, eight proteins were found to be causally associated with varicose veins, including COLEC11, IRF3, LUM, POSTN, RPN1, RSPO3, SARS2, and VAT1." (PMID 37404740, 2023). "We identified eight plasma proteins that are significantly associated with the risk of varicose veins after Bonferroni correction (P < 2.495 × 10−5), with five being protective (LUM, POSTN, RPN1, RSPO3, and VAT1) and three harmful (COLEC11, IRF3, and SARS2)." (PMID 37404740, 2023). "A comprehensive analysis indicated that IRF3, LUM, POSTN, RSPO3, and SARS2 might be potential drug targets for varicose veins." (PMID 37404740, 2023). "Five of eight proteins in primary analysis were finally identified as potential drug targets for varicose veins, including IRF3, LUM, POSTN, RSPO3, and SARS2." (PMID 37404740, 2023).
infection (26 papers, 2020 to 2025). The state of being infected such as from the introduction of a foreign agent such as serum, vaccine, antigenic substance or organism. "If the original SARS2-specific T cell associations with reduction of SARS2 NP RNA levels were only surrogates of time from infection (measured as days PSO), T cell associations should be lost upon adjustment for days PSO." (PMID 39704169, 2024). "The SARS2-NP R203K mutant, which contains two SUMOylation sites, showed higher poly-SUMOylation levels than SARS2-NP WT/K65R-R203K in an overexpression or recombinant VSVs infection setting." (PMID 38172120, 2024). "Nonetheless, 5–8 months after infection alone, SARS2-specific ASC were also excluded in LLPC, similar to the finding in our study after vaccination." (PMID 38559048, 2024). "Upon infection with VSVΔG*-SARS2, the 83 cell cultures displayed different sensitivities, with an overall transduction rate of 0–26.7%." (PMID 36690780, 2023). "We found that VSVΔG*-SARS2 can infect PK-15 cells (4.9%), but inconsistent conclusions were drawn by previous experimental infections." (PMID 36690780, 2023). "In this study, we had the opportunity to evaluate primary responses in SARS2-naive vaccinees, as well as secondary responses in SARS2-infected vaccinees with differing severities of primary infection." (PMID 36321826, 2022). "This study found key differences in the response to SARS2 vaccination depending on previous exposure and severity of primary infection." (PMID 36321826, 2022). "While we observed a reduction of vRNA in the NT at 6 dpc, a recent report showed that prior FLUAV infection 14 days before SARS2 infection resulted in reduced SARS2 replication in the lung of male 6–8 weeks old GSH." (PMID 36279276, 2022). "While SARS2 challenge led to overall higher pulmonary lesion scores later (6 days post challenge (dpc)) in infection than in the FLUAV pre-exposure group, FLUAV pre-exposed GSHs displayed slightly more pronounced pathology in the NT and lungs at 3 dpc." (PMID 36279276, 2022). "Surveillance for SARS2 has been recommended as a modality to limit transmission of infection from unvaccinated individuals with asymptomatic or pre-symptomatic infection." (PMID 36155639, 2022). "Time-course analysis of SARS2/SNFPP+CMP+TEV-H8STREPH6 expression in silkworm larvae after baculovirus infection showed that S protein in serum was highest at 5 days post-infection (dpi), but high mortality was observed at 5 dpi (data not shown)." (PMID 35095889, 2021). "Zooming in on a subset of the SARS2 consensome (orange box) affords an appreciation of the diversity of molecular classes that are transcriptionally regulated in response to SARS2 infection." (PMID 32963239, 2020). "Among the human-infecting CoVs, only the infection of SARS CoV 2 (SARS2) among humans resulted to a pandemic which would suggest that the protein structural conformation of SARS2 spike protein is distinct as compared to other human-infecting CoVs." (PMID 33585502, 2020). "While rVSV∆G/SARS2 titers peaked at 48 h following infection, the peak titer was orders of magnitude lower than peaks found with the other glycoproteins." (PMID 33348746, 2020). "Many zinc finger proteins are positively correlated with VSVΔG*-SARS2 infection rates." (PMID 36690780, 2023). "In those SARS2-infected subjects, severity of infection dictated plasma and nasal IgA responses in primary infection as well as response to vaccination (peak responses and durability), which could have implications for continued protection against reinfection." (PMID 36321826, 2022). "Regardless of the cause of the imprinting, it remains to be seen whether this will continue to newer strains and what effect reversing the order of SARS2 exposure (vaccination and then infection) will have on this." (PMID 36321826, 2022).
infection (continued). "Thus, our findings not only answer key questions on whether and how mechanical cues impact SARS2 viral entry and infection, but also provide valuable insights into the force-dependent dynamic spike/ACE2 interaction and the follow-up S1/S2 detachment." (PMID 34465913, 2021). "figshare File F1 contains the full human SARS1 (Section 2), SARS2 (Section 3), MERS (Section 4) and IAV (Section 5) infection transcriptomic consensomes." (PMID 32511379, 2020). "While the original wildtype SARS2 primary vaccine series and boosters have been effective against severe disease, hospitalization, and death, protection with sterilizing immunity against infection or transmission has not been entirely evident." (PMID 38559048, 2024). "While SARS2-VLPs failed to infect parental HEK293T cells, a significant increase in luciferase activity was observed in HEK293T-ACE2 cells following infection, indicating that SARS2-VLP target cell entry occurs in an ACE2-dependent manner." (PMID 40733630, 2025). "Moreover, only the supernatant of VeroE6 cells infected with IBIS, but not those with SARS2-mE nor wildtype SARS2, could inhibit VSV-GFP infection, suggesting that the protection was mediated by the IBIS-produced IFNβ." (PMID 37875475, 2023). "Titers permitted infections at an MOI of 1, and signal accumulated relatively fast, peaking at 5 h post infection At lower MOIs, we did not observe a second wave of luciferase produced, as seen with EBOV and LASV, which may relate to the poor titers produced with rVSV∆G/SARS2." (PMID 33348746, 2020).
cancer (4 papers, 2020 to 2024). A tumor composed of atypical neoplastic, often pleomorphic cells that invade other tissues. "While SARS1 is altered with a low frequency (1.5%) of both amplifications and deletions, the alterations of SARS2 in cancer patients are more frequent (2.8%) and mostly consist of gene amplifications." (PMID 33266490, 2020).
renal disease (3 papers, 2015 to 2025). "Only two mt-ARS deficiencies are primarily associated with extra-CNS manifestations: SARS2, linked to renal disease, and YARS2, which causes the MLASA2 phenotype." (PMID 41404429, 2025). "Renal disease has also been observed in patients with mutations in SARS2, the gene encoding the mitochondrial seryl-tRNA synthetase." (PMID 25629079, 2015).
SARS2 also shares sentences with these, for which no sentence is quoted: hyperuricemia (4 papers); mitochondrial disease (4); hypertrophic cardiomyopathy (2); renal failure (2); sarcoma (2); synovial sarcoma (2); tumor (2); Alkalosis (1); allergies (1); breast carcinoma (1); Ewing sarcoma (1); hearing loss (1); Hypomagnesemia (1); influenza (1); leukemia (1); lung carcinoma (1); Middle East respiratory syndrome (1); myopathy (1); Perrault syndrome (1); Pleuritis (1); renal dysfunction (1); Respiratory distress (1).